DMD (dystrophin)
Diseases named in the same sentence as DMD in open-access papers (continued):
Sharing a sentence is not in itself a finding about the gene and the disease.
Duchenne muscular dystrophy (continued). "Mutations in the dystrophin gene lead to either Duchenne Muscular Dystrophy (DMD) or Becker Muscular Dystrophy." (PMID 36505053, 2022). "The mdx-type models of Duchenne muscular dystrophy are based on the spontaneous mdx-23 mouse which is characterized by a point mutation in exon 23 of the DMD gene." (PMID 36362832, 2022). "These RNase H-independent ASOs act on the mRNA-encoding dystrophin protein in Duchenne muscular dystrophy and partially restore the function of the defective dystrophin protein by skipping specific exons." (PMID 36559141, 2022). "Duchenne muscular dystrophy (DMD) is an X-linked recessive progressive muscular disease marked by developmental delays due to mutations in the DMD gene, which encodes dystrophin." (PMID 36315559, 2022). "Duchenne muscular dystrophy (DMD) is a progressive muscle-wasting disorder caused by mutations in the dystrophin gene." (PMID 36444978, 2022). "Duchenne muscular dystrophy is a lethal muscle disease, caused by mutations in the gene encoding dystrophin, an actin-binding cytoskeletal protein." (PMID 36372234, 2022). "Duchenne muscular dystrophy is caused by the loss of functional dystrophin that secondarily causes systemic metabolic impairment in skeletal muscles and cardiomyocytes." (PMID 36142572, 2022). "Loss of function in the DMD gene encoding Dystrophin causes Duchenne muscular dystrophy, a rare but distinctive disease characterized by progressive muscle weakness and wasting primarily in males." (PMID 35419431, 2022). "Morpholino-based antisense oligomers are a best-in-class technology for the therapeutic modulation of splicing, and their use is now approved to treat Duchenne Muscular Dystrophy caused by specific defects in the dystrophin gene." (PMID 36077211, 2022). "DMD, the Duchenne muscular dystrophy gene, encodes dystrophin protein and is known for its role in the disease of the same name." (PMID 36110953, 2022). "Here, we report a case of an Indian neonate born with ambiguous genitalia diagnosed prenatally by ultrasound who had a karyotype of 45,X/46,XY and who also had Duchenne muscular dystrophy caused by a de novo mutation in the DMD gene." (PMID 36430887, 2022). "P101 was a 3-year-old boy with a hemizygous indel in DMD, associated with Duchenne muscular dystrophy, and a heterozygous missense variant in MYH7, associated with distal myopathy." (PMID 35628876, 2022). "Duchenne Muscular Dystrophy (DMD) is an X-linked disorder caused by mutation in the dystrophin gene." (PMID 36104592, 2022). "Duchenne muscular dystrophy (DMD) is a progressive disease caused by the loss of function of the protein dystrophin." (PMID 36555721, 2022). "Duchenne muscular dystrophy (DMD) is caused by loss-of-function mutations in the dystrophin gene on chromosome Xp21." (PMID 35163475, 2022). "Duchenne muscular dystrophy (DMD) is a lethal disease caused by X-linked mutations in the dystrophin gene." (PMID 35978142, 2022). "One example is Duchenne muscular dystrophy (DMD), in which the skeletal and cardiac muscle cells are affected and less able to produce dystrophin due to a mutation in the DMD gene." (PMID 35890005, 2022). "Duchenne muscular dystrophy (DMD), the most common X-linked inherited muscular disease, is caused by mutations in the DMD gene, leading to dystrophin deficiency that results in skeletal muscle fibre injury and progressive muscle wasting and weakness." (PMID 35436319, 2022). "When Xp21 is lost, NR0B1, which causes X-linked AHC, GK, which causes glycerol kinase deficiency, and in certain circumstances, DMD are also lost (resulting in Duchenne muscular dystrophy)." (PMID 36497046, 2022). "Duchenne muscular dystrophy (DMD) is a life-threatening disorder that is caused by the absence of functional dystrophin protein, resulting cell membrane fragility, muscle damage, inflammation, fibrosis, and ultimate degeneration." (PMID 35915850, 2022).
Duchenne muscular dystrophy (continued). "Artificial manipulation of mRNA splicing with an antisense oligonucleotide, such as those used for Duchenne muscular dystrophy therapy to skip mutated exon of dystrophin mRNA, can be applied in the future to enhance exon 17 exclusion." (PMID 36164503, 2022). "Dystrophin Dp71 is an isoform produced from the Dp71 promoter in intron 62 of the DMD gene, mutations in which cause Duchenne muscular dystrophy." (PMID 35547811, 2022). "Duchenne muscular dystrophy is a genetic condition characterized by a progressive loss of skeletal muscle function due to sarcolemma instability resulting from a deficiency in dystrophin." (PMID 35625891, 2022). "Alterations in the expression of the Duchenne muscular dystrophy (DMD) gene have been associated with the development, progression and survival outcomes of numerous cancers including tumours of the central nervous system." (PMID 35217778, 2022). "Dystrophin has been known as a cause of Duchenne muscular dystrophy, yet dystrophin usually functions in protein complexes known as dystrophin-associated protein complex (DAPC)." (PMID 36233261, 2022). "Duchenne muscular dystrophy (DMD) is a progressive myopathy caused by mutations in the dystrophin gene on the X chromosome." (PMID 35803994, 2022). "Duchenne muscular dystrophy (DMD) is an X-linked recessive inherited disorder caused by the absence of the Dystrophin protein." (PMID 35858850, 2022). "Genetic mutations resulting in the ablation of dystrophin protein give rise to Duchenne Muscular Dystrophy (DMD), a rare muscle wasting disorder with an estimated global prevalence of 4.8 per 100,000." (PMID 36076964, 2022). "Mutations in the DMD gene cause dystrophinopathies, including severe Duchenne muscular dystrophy of early childhood and its more benign and later onset form named Becker’s muscular dystrophy." (PMID 36362832, 2022). "Among the mutations arising in the DMD gene and causing Duchenne Muscular Dystrophy (DMD), 10–15% are multi-exon duplications." (PMID 35260651, 2022). "Duchenne muscular dystrophy (DMD) patients, having mutations of the DMD gene, present with a range of neuropsychiatric disorders, in addition to the quintessential muscle pathology." (PMID 34101068, 2022). "Adenine base editing has been successfully used to correct the DMD gene (dystrophin) mutations that are associated with Duchenne muscular dystrophy." (PMID 36032737, 2022). "Gene mutations causing loss of dystrophin result in the severe muscle disease known as Duchenne muscular dystrophy (DMD)." (PMID 36099033, 2022). "Duchenne muscular dystrophy (DMD) is a life-threatening disease caused by mutations in the dystrophin gene that significantly reduces life span, mainly due to either respiratory or cardiac failure." (PMID 35267907, 2022). "Duchenne muscular dystrophy (DMD) is a recessive X-linked hereditary disease caused by mutations (most often frameshifting deletions and insertions) in the DMD gene encoding the dystrophin protein." (PMID 36365155, 2022). "In Duchenne muscular dystrophy, dystrophin loss leads to chronic muscle damage, dysregulation of repair, fibro-fatty replacement, and weakness." (PMID 36123393, 2022). "In the case of Duchenne muscular dystrophy, which is caused by mutations in the dystrophin-coded gene, the gene therapies to replace, restore, or exon skipping of the affected gene have been developed and appear to be effective." (PMID 35163674, 2022). "Duchenne Muscular Dystrophy (DMD) is a lethal disease caused by mutations in dystrophin encoding gene, causing progressive degeneration of cardiac, respiratory, and skeletal muscles leading to premature death due to cardiac and respiratory failure." (PMID 35590083, 2022). "Duchenne muscular dystrophy (DMD) is a striated muscle degenerative disease due to loss of functional dystrophin protein." (PMID 35837290, 2022).
Duchenne muscular dystrophy (continued). "Duchenne muscular dystrophy is the most common form of muscular dystrophy arising from nonsense mutations in the structural protein dystrophin leading to its loss of function." (PMID 35646075, 2022). "Duchenne muscular dystrophy (DMD) is caused by mutations in the dystrophin gene, which mostly affects boys." (PMID 35662779, 2022). "Duchenne muscular dystrophy is an inherited disease characterized by progressive muscle wasting due to mutations in the DMD gene coding for the dystrophin protein." (PMID 35419381, 2022). "Duchenne Muscular Dystrophy is an X-linked recessive neuromuscular disorder caused by mutations in the dystrophin gene with the incidence of approximately 1 in 3,500–5,000 newborn boys." (PMID 35590083, 2022). "The X‐linked inherited neuromuscular disorder Duchenne muscular dystrophy is characterised by primary abnormalities in the membrane cytoskeletal component dystrophin." (PMID 35902360, 2022). "The dystrophin gene is responsible for Duchenne muscular dystrophy (DMD), an X-linked disease characterized by the atrophy of the muscles." (PMID 36429042, 2022). "Duchenne muscular dystrophy (DMD) is a severe form of dystrophin-associated muscular dystrophies, with early childhood onset." (PMID 35168641, 2022). "Duchenne muscular dystrophy (DMD) is an X-linked genetic disorder caused by mutations within the DMD gene, leading to progressive muscle fiber necrosis and muscle wasting and weakness." (PMID 35615709, 2022). "Deficiency in the membrane cytoskeletal protein dystrophin is the underlying cause of the progressive muscle wasting disease named Duchenne muscular dystrophy." (PMID 36362832, 2022). "Duchenne muscular dystrophy (DMD) is a progressive hereditary disease caused by the absence of the dystrophin protein." (PMID 36365155, 2022). "Duchenne muscular dystrophy (DMD) is a fatal muscle-wasting disorder caused by mutations in the Dystrophin gene and for which there is currently no cure." (PMID 35468843, 2022). "A method to isolate and sequence individual nuclei from human and mouse muscle biopsies provides further insight into the mechanisms of dystrophin loss and repair, in the context of Duchenne muscular dystrophy." (PMID 36123393, 2022). "Duchenne muscular dystrophy (DMD) is a fatal muscle wasting disease caused by deficiency in dystrophin, a protein product encoded by the DMD gene." (PMID 34575126, 2021). "PTC124 (also known as ataluren or Translarna) has received NICE (National Institute for Health and Care Excellence) approval for Duchenne muscular dystrophy treatment caused by nonsense mutations in the dystrophin gene." (PMID 33445564, 2021). "Duchenne Muscular Dystrophy (DMD) is a devastating X-linked disease caused by mutations in the dystrophin gene." (PMID 34680564, 2021). "Duchenne muscular dystrophy (DMD) is an early onset, severely progressive muscle wasting disease, caused by variants in the DMD gene that cause premature truncation of dystrophin protein translation." (PMID 32391605, 2021). "Duchenne muscular dystrophy (DMD) is a genetic neuromuscular disorder caused by mutations in the dystrophin gene." (PMID 33910603, 2021). "Duchenne muscular dystrophy is a progressive and lethal X-linked recessive neuromuscular disease caused by mutations in the dystrophin gene." (PMID 34064562, 2021). "In clinical trials, CD8+ T cell responses have been observed against dystrophin and α1-antitrypsin in treatment of Duchenne’s muscular dystrophy and α1-antitrypsin (AAT) deficiency, respectively." (PMID 34135899, 2021). "Despite low in vivo efficacy, PTC124 has been approved in the European Union for ambulatory patients aged 2 years and older with Duchenne muscular dystrophy resulting from nonsense mutations in the dystrophin gene." (PMID 33567469, 2021).
Duchenne muscular dystrophy (continued). "Duchenne muscular dystrophy (DMD) is a devastating congenital disorder caused by an X-linked recessive mutation in the DMD gene, inducing an absence or decreased expression of dystrophin in skeletal muscle and cardiac muscle cells." (PMID 34959441, 2021). "Duchenne muscular dystrophy (DMD) is a rare genetic disease due to dystrophin gene mutations which cause progressive weakness and muscle wasting." (PMID 34305639, 2021). "Duchenne muscular dystrophy (DMD) is an X-linked progressive disease characterized by loss of dystrophin protein that typically results from truncating mutations in the DMD gene." (PMID 33898631, 2021). "Duchenne muscular dystrophy (DMD) is an X-linked recessive disorder caused by mutations in the gene encoding the dystrophin protein." (PMID 34360780, 2021). "Duchenne muscular dystrophy (DMD) is an X-linked inherited disease caused by mutations in the gene encoding dystrophin that leads to a severe and ultimately life limiting muscle-wasting condition." (PMID 34930315, 2021). "This is the case for Duchenne muscular dystrophy (DMD), a degenerative muscle disease caused by mutations in the DMD gene encoding for the dystrophin protein, which causes an aberrant translation." (PMID 33917446, 2021). "Duchenne muscular dystrophy (DMD) is an X-linked muscle-wasting disease caused by the loss of dystrophin." (PMID 33897454, 2021). "This Duchenne muscular dystrophy animal has a nonsense mutation in exon 23 of the Dmd gene, which abolishes dystrophin production." (PMID 34850138, 2021). "Aged dystrophin-null canines are excellent models for studying experimental therapies for Duchenne muscular dystrophy, a lethal muscle disease caused by dystrophin deficiency." (PMID 34704592, 2021). "Duchenne muscular dystrophy (DMD) is a progressive neuromuscular disorder caused by loss of dystrophin." (PMID 33963238, 2021). "Duchenne is an X-linked condition caused by deletions or mutations in the DMD (Duchenne muscular dystrophy) gene, which encodes the dystrophin protein." (PMID 34311756, 2021). "Patients with Duchenne muscular dystrophy (DMD) lack sufficient expression of a functional dystrophin protein in all striated muscles, leading to loss of ambulation by 13 years of age, progressive respiratory insufficiency and dilated cardiomyopathy." (PMID 33949649, 2021). "Myopathies are a set of neuromuscular diseases, the most common of which is Duchenne’s muscular dystrophy (1 in 3300 newborn babies) resulting from mutations in the dystrophin gene (DMD)." (PMID 33959146, 2021). "Duchenne muscular dystrophy is a highly progressive muscle wasting disorder due to primary abnormalities in one of the largest genes in the human genome, the DMD gene, which encodes various tissue-specific isoforms of the protein dystrophin." (PMID 34553265, 2021). "Duchenne muscular dystrophy (DMD) is a X-linked myopathy caused by the deficiency of dystrophin protein." (PMID 34575096, 2021). "These deletions are outside the major hotspot region of exons 45–53 for DMD mutations in Duchenne muscular dystrophy patients and appear to be tumour-specific mutational events." (PMID 33188621, 2021). "A similar therapeutic strategy is also intensively tested for treating Duchenne muscular dystrophy (DMD), the most common form of muscular dystrophy caused by mutations in the DMD gene." (PMID 33594520, 2021). "Duchenne muscular dystrophy (DMD) is caused by mutations in the DMD gene and is inherited in an X-linked recessive fashion." (PMID 34220666, 2021). "Duchenne muscular dystrophy (DMD) is an x-linked recessive disorder that is caused by loss-of-function mutations in the DMD gene." (PMID 34440535, 2021). "Duchenne muscular dystrophy (DMD) is an incurable disease caused by out-of-frame DMD gene deletions while in frame deletions lead to the milder Becker muscular dystrophy (BMD)." (PMID 34498054, 2021).
Duchenne muscular dystrophy (continued). "Duchenne muscular dystrophy (DMD) is caused by dystrophin gene mutations leading to skeletal muscle weakness and wasting." (PMID 34516770, 2021). "Duchenne muscular dystrophy (DMD) is an X-linked recessive neuromuscular disorder caused by absence of dystrophin protein." (PMID 33389442, 2021). "Duchenne muscular dystrophy is one of the most common and severe forms, and is caused by a mutation in the gene encoding for dystrophin protein." (PMID 34205021, 2021). "Additional variants in aunt were present in DMD (Duchenne muscular dystrophy), POMGNT2 (dystrophy-dystroglycanopathy type A8) that are not involved in cardiac pathology." (PMID 33829027, 2021). "Duchenne muscular dystrophy (DMD) is a fatal neuromuscular disorder that occurs due to inactivating mutations in DMD gene, leading to muscular dystrophy." (PMID 34472584, 2021). "Duchenne muscular dystrophy (DMD) is a genetic, X-linked, muscle-wasting disorder that affects 1:3500–5000 boys and is caused by mutations in the DMD gene." (PMID 33407808, 2021). "The safety and therapeutic efficacy of AON-induced skipping of native exons has been explored most thoroughly for Duchenne muscular dystrophy (caused by mutations in the DMD gene), and two AON-based treatments have recently obtained market approval by the FDA." (PMID 34502064, 2021). "The use of CRISPR–Cas gene-targeted editing successfully removed Duchenne muscular dystrophy causing mutations in dystrophin proteins." (PMID 33805113, 2021). "Duchenne muscular dystrophy (DMD) is caused by loss of the membrane-associated protein dystrophin, and mutations in genes encoding dystrophin-associated proteins such as the sarcoglycans elicit a similar phenotype." (PMID 34516828, 2021). "Becker muscular dystrophy (BMD) is the milder allelic variant of Duchenne muscular dystrophy, with higher dystrophin levels." (PMID 33723284, 2021). "Duchenne muscular dystrophy (DMD) is an X-linked recessive disease caused by a mutant dystrophin protein." (PMID 34424816, 2021). "Duchenne muscular dystrophy (DMD) is a muscular dystrophy caused by a mutation of the dystrophin gene." (PMID 33935716, 2021). "At present, the mainstream theory about the muscle degeneration and fibrosis causes of Duchenne muscular dystrophy is that the integrity of the dystrophin protein in muscle cell membrane is lost and destroyed." (PMID 35174208, 2021). "Here, we used a single or repeated muscle regeneration model using CTX and mdx mice, a mouse model of Duchenne muscular dystrophy caused by a mutation in the dystrophin gene." (PMID 33807264, 2021). "Duchenne muscular dystrophy (DMD) is caused by a dystrophin deficiency (Dys), which results from mutations in the DMD gene." (PMID 33578948, 2021). "Duchenne muscular dystrophy (DMD) is a progressive muscle-wasting disease caused by out-of-frame or nonsense mutation in the dystrophin gene." (PMID 34698059, 2021). "Human Dystrophin gene is a causative gene for Duchenne Muscular Dystrophy and spans megabases with gigantic introns rich in repetitive DNA as in the Drosophila kl genes." (PMID 34181646, 2021). "In hearts from mdx mice [dystrophin-deficient mice as an animal model of Duchenne muscular dystrophy (DMD)], the percent of mitochondria with loss of cristae was increased both at 3–4 months of age and at 12 months of age compared to WT." (PMID 35822027, 2021). "Duchenne muscular dystrophy (DMD) is a progressive muscle-degenerative disease caused by the absence of functional dystrophin protein." (PMID 34305644, 2021). "Duchenne muscular dystrophy (DMD) is a devastating X-linked muscle disease that is caused by mutations in the DMD gene and affects 1 of 5000 male infants." (PMID 34627382, 2021). "Mutations in Dystrophin, one of the largest proteins in the mammalian body, are causative for a severe form of muscle disease, Duchenne Muscular Dystrophy (DMD), affecting not only skeletal muscle, but also the heart." (PMID 33531685, 2021).